IL17A (interleukin 17A)
Diseases named in the same sentence as IL17A in open-access papers (continued):
Sharing a sentence is not in itself a finding about the gene and the disease.
cancer (continued). "Th17 cells are generally important mediators of inflammation, autoimmune diseases and cancer, particularly through the production of IL-17A and IL-17F." (PMID 22461912, 2012). "For instance, an increased number of IL-17A producing cells have been detected in different types of cancer." (PMID 22855687, 2012). "Since overexpression of MMPs plays an important role in cancer metastasis, we next investigated the role of IL-17A on MMPs expression in HCC cell lines." (PMID 21760911, 2011). "Recently, the effect of IL-17A on cancer progression has been addressed and results were controversial." (PMID 21760911, 2011). "IL-17A deficiency impairs osteoclast differentiation and osteolytic activity, indicating that targeting IL-17A could be a promising therapeutic strategy for treating cancer-related bone metastasis." (PMID 40536951, 2026). "Moreover, rescue assays further confirmed the cancer-promoting role of IL-17 signaling in PCa by using recombinant human IL-17 A stimulations." (PMID 40055805, 2025). "In this study, we aimed to demonstrate that IL17A depletion represents a new approach to increase the intensity of an antigen‐specific cytotoxic and humoral response and, therefore, the effectiveness of a cancer vaccine applied in the treatment of PDA." (PMID 40831074, 2025). "In cancer-induced bone pain, treatment with IL-17A antibody in the spinal cord of female rats could also inhibit cancer-induced mechanical allodynia and thermal hyperalgesia." (PMID 40332543, 2025). "IL-17A is involved in several diseases, like inflammatory diseases, human rheumatoid arthritis, psoriasis, neurodegenerative diseases, and different kinds of cancers." (PMID 40136958, 2025). "The cancer-related need for support, combined with the mechanisms described in the “erosion model”, likely accounts for the positive correlations observed between the support-based coping strategies and IL-17a and IL-10 at T2 in the total sample." (PMID 41153842, 2025). "Because RT is toxic and causes tissue injury, identifying the effect of IL-17A in different tissues may help researchers and clinicians understand the immunopathogenesis of RITI in patients with cancer after RT." (PMID 41229527, 2025). "Among the other interleukins, interleukin IL-17A is associated with inflammations, neurodegenerative diseases, and cancers, and no biosensors have been previously reported for its detection." (PMID 40136958, 2025). "In addition, IL-17A upregulation was detected in sepsis, pneumonia, allograft rejection conditions, and notably in cancer." (PMID 40064794, 2025). "Pathway analysis revealed diminished responses to oxygen‐containing compounds, lipopolysaccharide, and bacteria in PDAC with elevated DUOX2 expression, highlighting the potential involvement of IL‐17A signaling in modulating interactions between cancer and the microbiota." (PMID 38585232, 2024). "IL-17A is highly expressed in cancer cells and promotes tumorigenesis in NSCLC." (PMID 38394046, 2024). "By unraveling the intricate impact of IL‐17A signaling on microbial homeostasis, this study lays the groundwork for future research and therapeutic approaches aimed at fully leveraging IL‐17A‐targeting interventions in the cancer treatment." (PMID 38585232, 2024). "RT-qPCR was utilized for testing IL-17A expression in cancer tissues and cells." (PMID 38430256, 2024). "Furthermore, OLP decreases the number of viable cells during proliferation, the migratory potential (Scratch test), and the single cell capacity to grow within colonies as a cancer phenotype in A549 cells exposed to IL-17A." (PMID 38999871, 2024). "We thus investigated whether IL‐17A influences the TNF‐driven adhesion of cancer cells to a mesothelial monolayer in vitro." (PMID 38566518, 2024). "This process promotes osteoclast differentiation, suggesting that IL-17A could be a potential therapeutic target for managing bone resorption in cancer patients." (PMID 39125732, 2024).
cancer (continued). "IL17A influenced the level of IL33 in the cancer group (p = 0.007)." (PMID 38398137, 2024). "This study has uncovered a hitherto unknown mechanism involving the induction of mesenchymal reprogramming by the synergistic action of IL‐17A and TNF produced by Th17 cells, which renders the mesothelial monolayer susceptible to cancer cell adhesion." (PMID 38566518, 2024). "Th17 cells exert a protective activity toward the host in healthy subjects, although excessive production of IL-17A during chronic inflammation may promote the development of autoimmune diseases and cancer." (PMID 38999871, 2024). "In addition, we intratumorally injected the Secukinumab (3 mg/kg) or PBS to validate the IL-17a’s cancer-promoting ability." (PMID 38740736, 2024). "IL-17A expression correlates with a better prognosis and improved patient survival in a variety of cancers, suggesting that IL-17 may have antitumour effects." (PMID 37211606, 2023). "IL-17A mediates cancer cell invasiveness and metastasis via MMP-2, MMP-9, and MMP-13." (PMID 36993955, 2023). "The immunomodulatory potential of IL-17A provides an attractive target for cancer immunotherapy." (PMID 37211606, 2023). "Similarly, chemotherapy has been shown to increase the number of cancer-associated fibroblasts in CRC, which in turn release the pro-inflammatory cytokine IL-17A." (PMID 37884500, 2023). "In cancer studies, IL-17A has also been shown to play a role in VEGF-driven angiogenesis." (PMID 36675261, 2023). "Taken together, our observations reported herein and studies in the literature suggest that targeting IL-17A in combination with immune checkpoint inhibitors may thwart resistance mechanisms and lessen adverse autoimmune events in cancer patients." (PMID 36480166, 2023). "Moreover, after IL-17A treatment of these cancer cells, N-terminal GSDMD protein levels were increased." (PMID 37211606, 2023). "A study demonstrated that IL-17A could enhance cancer cell proliferation, metastasis, and micro-angiogenesis in BC by multiple pathways." (PMID 38129538, 2023). "It has been reported that cancer cells (HeLa, A549, and Myc-Cap/CR) treated with IL-17A induced more M2 polarization of RAW264.7 and THP-1 cells, which may be a result of the cyclooxygenase 2/prostaglandin E2 (COX-2/PGE2) pathway in the cancer cells." (PMID 37067414, 2023). "Finally, more clinical evidence is needed to demonstrate the correlations between C. albicans, IL-17A/IL-17-RA, macrophage, and cancer." (PMID 37067414, 2023). "Characterization of the sensitivity and specificity of different IL17A antibodies will have to be done to reduce the potential cross-reactivity with other IL-17 isoforms, since different IL-17 isoforms can activate different signaling pathways even within the same cancer type." (PMID 37427128, 2023). "There is evidence from clinical studies to suggest that IL-17A signaling undermines immune checkpoint inhibitors, contributes to immunotherapy resistance, and promotes the development of adverse autoimmune events in cancer patients." (PMID 36480166, 2023). "The results suggested that cancer cells were highly expressing IL-17A." (PMID 37978543, 2023). "Interestingly, IL-17A has been known to increase the immunosuppressive activity of Tregs and promote the recruitment of MDSCs in cancer." (PMID 35873573, 2022). "Additionally, PM characterized by abundant fibrous stroma is considered to be caused by crosstalk between cancer cells and CAFs with Transforming growth factor β (TGF-β), or between mast cells and CAFs by interleukin-17A (IL-17A)." (PMID 34997450, 2022).
cancer (continued). "The positive association of serum IL-17A with LDL-C through the perturbation of IL-17A levels, as well as IL-23 levels, may pave the road for the development of MetS and cancer." (PMID 36140808, 2022). "Mean value of IL17A was significantly higher in HNSCC compared to other types of cancer." (PMID 36405727, 2022). "The IL-17A response functions as a double-edged sword were suggested in cancers." (PMID 35902909, 2022). "The coculture of CD4 Th cell lines from C5 with SW480 cell line showed a lower level of IL-17A because the SW480 cancer cells underwent apoptosis while high IL-6 was detected due to the high proliferation of CD4 Th cell lines from C5 which cause the cell cytotoxicity." (PMID 37529004, 2022). "While IL-17A clearly plays a key role in protecting mucosal surfaces from bacterial, helminth and fungal infection, it has been reported to have both pro- and anti-tumorigenic roles in cancer." (PMID 35269931, 2022). "IL-17A, produced mainly by T helper 17 cells, is involved in host defense against microbial organisms and in the development of immune-mediated inflammatory diseases and cancer." (PMID 36359251, 2022). "Moreover, IL-17A can synergize with many other inflammatory stimuli, further enhancing its activity and promoting the transition of inflammation to cancer." (PMID 35991881, 2022). "For example, a dysregulated IL-17A and IL-17F production can impair myeloid cell recruitment and determine an excessive pro-inflammatory cytokine expression, and consequently chronic inflammation, which leads to cancer development." (PMID 36432658, 2022). "While IL-17A acts as a potent inducer of T-cell-mediated antitumor immune responses, this cytokine was described as an essential activator of angiogenic factors, as well as an inducer of the proinflammatory factors IL-6 and IL-8 in cancer." (PMID 34830027, 2021). "Moreover, we observed a marked increase in the expression of IL-23R and IL-17A in both cancer cell lines when co-cultured with educated macrophages as compared to uneducated macrophages." (PMID 34680308, 2021). "Moreover, we observed a marked increase in the expression of IL-23R and IL-17A in both cancer cell lines when co-cultured with educated DCs as compared to uneducated DCs." (PMID 34680308, 2021). "Thus, ETBF induces the recruitment and proliferation of CD4+CCR6+IL17A+ Th17 cells via the IL-17 signaling pathway, thereby participating in tumorigenesis and cancer cell growth." (PMID 35069592, 2021). "In future, it will be interesting to investigate whether the stimulating role of Il17a/f1 is only specific to kras-induced cancer or universally to most other cancers." (PMID 33446803, 2021). "High levels of IL-17A in various cancer types, including NSCLC, were reported." (PMID 33802737, 2021). "Similarly, high expression levels of many interleukins including IL6, IL7, CXCL8/IL8, IL11, and IL17A/IL17 are correlated with increased platinum resistance or poor clinical outcome in several types of cancer." (PMID 34645978, 2021). "Collectively, our data have shown that cholangiocytes could accelerate HCC progression through Il17a/f1 cytokine which could be a potential target for cancer therapy." (PMID 33446803, 2021). "Furthermore, IL17A is involved in immune responses and inflammation, but also promotes migration and invasion in cancer cells." (PMID 33690729, 2021). "Therefore, it is possible that mast cells prolong local IL-17A release, which links mast cells to the immunopathogenic functions of IL-17A in cancers." (PMID 33922465, 2021). "The higher concentration of IL-17A in the peritoneal fluid of OC patients noted in our study may contribute to local dissemination of cancer by affecting the formation of peritoneal implants." (PMID 32148497, 2020). "IL-17A, a best-characterized member of the IL-17 family, exerts diverse immune functions, including host defense from infection, tissue remodeling and repair, regulation of immune cell homing and inflammation, and cancer progression." (PMID 33304351, 2020).
cancer (continued). "As a member of IL-17 family, IL-17A was reported to have controversial roles in cancer." (PMID 32489459, 2020). "Finally, we observed that CCL20 and IL-17A levels were both positively associated with levels of CD44 and MMP3, which are closely related to cancer progression." (PMID 31387598, 2019). "In addition to proinflammatory cytokines, we also measured key Th1 (IFN-γ, IL-12) and Th17 (IL-17A) cytokines involved in the control of infections and cancer by the immune system." (PMID 31835366, 2019). "A. The expression of CCL20 and IL-17A from TCGA database in 18 kinds of cancer tissues." (PMID 31387598, 2019). "Interleukin‐17A (IL‐17A) plays an important role in various inflammatory diseases and cancers." (PMID 30353649, 2019). "Myeloid expression of IL-17A in the spleen has been published as a sign of advanced cancer." (PMID 31881770, 2019). "Additionally, IL-17A was shown to promote the invasion of cancers cells, such as breast and gastric cancer cells." (PMID 29983876, 2018). "However, its role and function in inflammation and cancer, a priori close to those of IL-17A, need to be further investigated." (PMID 28347290, 2017). "In colon cancer, these two cytokines could have in fact opposite effects since IL-17A favors cancer development and IL-17F appears to be a protective factor against tumorigenesis." (PMID 28347290, 2017). "IL-17A is a pleiotrophic inflammatory cytokine that has multi-faceted roles in cancer." (PMID 28562353, 2017). "In addition, we showed that IL-17A enhanced cancer cell proliferation, which was significantly inhibited by cordycepin." (PMID 29212184, 2017). "Elucidating the role of the IL-17A/miR-23b/versican pathway might enlarge our understanding of the interaction between inflammatory microenvironment and cancer progression, which can be exploited for potential immunotherapeutic and diagnostic target in TSCC." (PMID 28035060, 2017). "The top 10 canonical pathways determined by IPA reveal important mechanisms that may potentiate cancer development in the T. gondii-infected brain, such as Wnt/Ca + (14 genes) and inflammatory IL-17A (14 genes) pathways." (PMID 28904337, 2017). "The aim of this study was to quantitatively summarize the association between intratumoral IL-17A and clinical outcomes in cancer patients, and thereby provided more evidence on the clinical value of IL-17A as a prognostic biomarker and therapeutic target for solid malignances." (PMID 29029520, 2017). "Recently, the role of IL-17A has been investigated in several cancer types." (PMID 28035060, 2017). "IL-17A can stimulate cancer cell proliferation, which can be suppressed by cordycepin." (PMID 29212184, 2017). "It has been well identified that IL-17A plays an important role in promoting cancer growth." (PMID 27176825, 2016). "Few studies have examined the role of IL17A / F in the treatment of cancer." (PMID 26083022, 2015). "Moreover, cytotoxic treatment can increase both CAF percentage and cytokine secretion, especially IL-17A, both of which contribute to cancer-initiating cells growth and therapeutic resistance." (PMID 26560147, 2015). "IL-17A plays an important role in many inflammatory diseases and cancers." (PMID 25250801, 2014). "IL-17A has been found to be closely correlated with the metastasis of cancer." (PMID 25244643, 2014). "IL-17A was also found to be correlated with the invasion of cancer cells." (PMID 25244643, 2014). "The role of IL-17A in the development and progression of these cancers remains controversial." (PMID 25250801, 2014). "Among these, IL-17A has been detected in several human cancers." (PMID 25181290, 2014). "The proinflammatory cytokines IL-17A and IL-17F can mediate inflammation and cancer." (PMID 22461912, 2012). "Similarly, studies in cancer models have shown a dual role of IL-17A in controlling neoplastic cell growth." (PMID 23109839, 2012). "The role of IL-17A in the development and progression of cancer remains controversial." (PMID 21760911, 2011).
cancer (continued). "In contrast, for poorly differentiated (G3) tumors, IL-17A levels remained consistently lower and showed a steeper, continuous decline with increasing IL-8, indicating an attenuated or dysregulated inflammatory response characteristic of more aggressive cancers." (PMID 40725273, 2025). "Therefore, longitudinal studies to validate the value of IL-17A as a biomarker of RT-induced tissue inflammation and RITIs are needed, which will ultimately improve the therapeutic response and clinical outcomes in patients with cancer undergoing RT." (PMID 41229527, 2025). "In poorly differentiated tumors (G3, green dashed line), IL-17A levels remained consistently lower across the range of IL-8 concentrations and showed a steeper, continuous decline as IL-8 increased, indicating an attenuated or dysregulated inflammatory response in these more aggressive cancers." (PMID 40725273, 2025). "Therefore, we suspect that the presence of M. globosa may lead to the overexpression of IL-17A and chronic inflammation, which ultimately promotes cancer progression." (PMID 39235230, 2024). "Moreover, the regulatory functions of IL-17A in various cancers have also been confirmed." (PMID 38430256, 2024). "Moreover, we observed that cancer patients had higher interleukin 17A levels than healthy patients." (PMID 38398137, 2024). "IL‐17A and TNF synergistically induced the reprogramming of mesothelial cells towards a pro‐inflammatory mesenchymal phenotype, concomitantly with a loss of tight junctions and an impairment of mesothelial monolayer integrity, thereby promoting cancer cell adhesion." (PMID 38566518, 2024). "The authors clearly indicated that the levels of Th17 cells and IL-17A mRNA were increased in NSCLC patients (both in blood and cancerous lung tissue), and in vitro studies revealed that IL-17A could promote the invasion, migration, and cancer stem cell-like properties of NSCLC cells." (PMID 37894302, 2023). "The IL-17 family of cytokines is composed of six members named IL-17A (commonly known as IL-17), IL-17B, IL-17C, IL-17D, IL-17E (also known as IL-25), and IL-17F with different sequence homology and functions that are important players in host defense responses, inflammation, and cancer development." (PMID 38068860, 2023). "Similarly, involvement of IL-17A in metastatic processes is well documented in cancer research." (PMID 36034693, 2022). "Therefore, the potential biological function of IL17A may have two sides in individual cancer types of HNSCC." (PMID 35902909, 2022). "Furthermore, IL-17A secreted by T cells was found to play a direct role in cancer cell sensitivity to DOX however transcriptional alterations as a result of IL-17A in cancer cells also likely contributed to signaling cascades inducing T cell exhaustion, recruitment and activation." (PMID 35924165, 2022). "Here, we intentionally overlook IL-17A, and we focus instead on the role of the other cytokines of the IL-17 family in the interplay between microbiota and epithelial cells that may contribute to cancer pathogenesis and immune surveillance." (PMID 33244315, 2020). "Thus, the microbiota-IL-17A axis is also relevant in cancer patients." (PMID 33244315, 2020). "Therefore, GLK overexpression in T cells or other cell types may also induce overproduction of IL-17A in tumor microenvironment, leading to cancer metastasis." (PMID 31640697, 2019). "Furthermore, IL-17A was shown to promote the migration and invasion of cancer cells by up-regulating the expression of MMP-9 and down-regulating the expression of the tissue inhibitor of metalloproteinase 2 (TIMP2)—a natural inhibitor of MMPs—via the p38/NF-kB signaling pathway." (PMID 29983876, 2018). "Moreover, IL-17A increased DNA synthesis in cancer cells, and cordycepin inhibited the effect, too." (PMID 29212184, 2017). "Therefore, to clarify the exact role of IL-17A in cancer biology is very important." (PMID 28035060, 2017).